BCAP29 (B cell receptor associated protein 29)
Description:
May play a role in anterograde transport of membrane proteins from the endoplasmic reticulum to the Golgi. May be involved in CASP8-mediated apoptosis (By similarity).
Synonyms: Bap29; DKFZp686M2086; B29
Tractability: Antibody: UniProt predicts a signal peptide or a membrane-spanning region. PROTAC: ubiquitination databases record sites on it; its protein half-life has been measured.
Gene: Protein-coding gene on chromosome 7 (107,579,957 to 107,629,170, forward strand). Ensembl gene ENSG00000075790.
Subcellular location: Endoplasmic reticulum membrane
Subcellular location (Human Protein Atlas): Cytosol
Gene Ontology:
Molecular function: protein binding
Biological process: osteoblast differentiation; endoplasmic reticulum to Golgi vesicle-mediated transport; intracellular protein transport
Cellular component: membrane; endoplasmic reticulum; endoplasmic reticulum membrane
Genetic constraint (gnomAD): Loss-of-function variants: 16 observed, 15.15 expected, observed/expected ratio (o/e) 1.06, 90% interval 0.71 to 1.59. The upper end of that interval is the gene's LOEUF score, 1.59, which puts it in group 6 of 6, group 1 being the genes least tolerant of losing a copy. Missense variants: 182 observed, 169.39 expected, observed/expected ratio (o/e) 1.07, 90% interval 0.95 to 1.22. Synonymous variants: 65 observed, 60.56 expected, observed/expected ratio (o/e) 1.07, 90% interval 0.88 to 1.32.
Homologues: Orthologues: chimpanzee BCAP29 (96% identical), pig BCAP29 (87% identical), guinea pig BCAP29 (83% identical), mouse Bcap29 (82% identical), rat Bcap29 (82% identical), dog BCAP29 (78% identical), tropical clawed frog bcap29 (55% identical), zebrafish bcap29 (53% identical), Drosophila melanogaster CG13887 (33% identical), Caenorhabditis elegans Y54G2A.18 (32% identical). Paralogues in human: BCAP31 (49% identical).
Diseases named in the same sentence as BCAP29 in open-access papers:
BCAP29 is named in the same sentence as 11 diseases in open-access papers, as found by Europe PMC text mining. Sharing a sentence is not in itself a finding about the gene and the disease. The quoted sentences say what the papers report.
COVID-19 (1 paper, 2024). A disease caused by infection with severe acute respiratory syndrome coronavirus 2. "A mendelian randomization analysis of the association between SARS-CoV-2 infection and blood constituents found consistent evidence that COVID-19 is causally associated with BCAP29." (PMID 38674024, 2024).
Osteochondrosis (1 paper, 2023). Abnormal growth ossification centers in children. "Several CNVRs harboring genes, such as B cell receptor-associated protein 29 (BCAP29) and Wnt family member 9A (WNT9A), are located in osteochondrosis QTL regions." (PMID 38076560, 2023).
BCAP29 also shares sentences with these, for which no sentence is quoted: gastric cancer (7 papers); cancer (3); prostate carcinoma (3); Arthritis (1); autism (1); hand osteoarthritis (1); psychiatric disorder (1); schizophrenia (1); skin cancer (1).